BRD4 (bromodomain containing 4)
Diseases named in the same sentence as BRD4 in open-access papers (continued):
Sharing a sentence is not in itself a finding about the gene and the disease.
ovarian carcinoma (continued). "PRMT1 is highly expressed in ovarian cancer and is known to facilitate the methylation of bromodomain-containing protein 4 (BRD4), which is crucial for both early embryonic development and cancer progression." (PMID 39908270, 2025). "We confirm these results in OVSAHO ovarian cancer cells, where the overexpression of BRD4 isoforms significantly reduces tumor growth." (PMID 40112818, 2025). "BRD4 is also a critical regulator of cancer cell growth and survival, and studies in ovarian cancer cells have recently shown that BRD4 binds the promotor region of the IL-34 gene and regulates IL-34 production." (PMID 39451216, 2024). "BRD4 gene amplification has been identified in ovarian cancer (~18–19%) according to The Cancer Genome Atlas (TCGA) analysis." (PMID 38893083, 2024). "The most thoroughly studied BET protein is BRD4, which is amplified in ~18–19% of ovarian cancer cases according to The Cancer Genome Atlas (TCGA)." (PMID 38893083, 2024). "This study represents the initial exploration of the combination of a BRD4 inhibitor and the classic cytotoxic agent, cisplatin, in ovarian cancer cells." (PMID 38473320, 2024). "For example, BRD4, located at chromosome 19p13, was amplified in a considerable proportion (~20%) of ovarian cancers, and the expression of BRD4 correlated with amplification status." (PMID 39273015, 2024). "Despite efforts to use bromodomain inhibitors as anticancer drugs, few studies have investigated the correlation between BRD4 and ovarian cancer pathogenesis." (PMID 38473320, 2024). "The development of these new agents creates the imminent need to better characterize the role of the BRD4 gene in high-grade ovarian carcinoma." (PMID 38893083, 2024). "Our data are clinically relevant as we have revealed the possibility of overcoming the limitations of ovarian cancer treatment and the additive effect of a BRD4 inhibitor with the standard anticancer cisplatin." (PMID 38473320, 2024). "To evaluate BRD4 expression in ovarian cancer cell lines, we used the SKOV3, A2780, OVCAR3, and CAOV3 cell lines." (PMID 38473320, 2024). "For instance, BRD4 expression was upregulated in pediatric primary medulloblastomas and was found to be overexpressed in ovarian cancer, which is correlated with BRD4 amplification." (PMID 39273015, 2024). "Acknowledging these inherent limitations, our research endeavors are dedicated to investigating the efficacy of BRD4 inhibitors in the context of ovarian cancer." (PMID 38473320, 2024). "Our results suggest OPT-0139, a BRD4 inhibitor, as a promising anticancer drug for the treatment of ovarian cancer by inhibiting cell proliferation, decreasing cell viability, arresting cell cycle, and inducing apoptosis." (PMID 38473320, 2024). "Concerning ovarian cancer, a comprehensive analysis of The Cancer Genome Atlas (TCGA) database revealed that 9% of ovarian cancer patients exhibited elevated BRD4 expression." (PMID 38473320, 2024). "BRD4 gene amplification has been identified in ovarian cancer (~18–19%) according to The Cancer Genome Atlas (TCGA) analysis while increased BRD4 mRNA levels have been identified in 9% of ovarian cancers." (PMID 38893083, 2024). "This study investigated a new drug, OPT-0139, an inhibitor of BRD4, a protein involved in ovarian cancer." (PMID 38473320, 2024). "Inhibition of miR-598 or overexpression of BRD4 abrogated the function of circCELSR1 in ovarian cancer." (PMID 38152652, 2023). "Another study showed that knockdown of circCELSR1 reduced invasion, migration, proliferation and EMT and stimulated apoptosis via binding to miR-598 and upregulation of BRD4 in ovarian cancer cells." (PMID 38152652, 2023). "Here, we described the consequences of BRD4-L and BRD4-S overexpression in ovarian carcinoma shedding a light on a complex regulation of BRD4 isoforms." (PMID 37705995, 2023). "We next aimed to evaluate the relationship between BRD4 methylation and ovarian cancer cell metastasis in vitro." (PMID 37737256, 2023).
ovarian carcinoma (continued). "Analysis of BRD4 isoforms in malignancies other than ovarian carcinoma has suggested that BRD4 isoforms play distinct roles in carcinogenesis." (PMID 37705995, 2023). "The results showed that PRMT1 and BRD4 are markedly overexpressed in ovarian cancer tissues compared to normal tissues." (PMID 37737256, 2023). "AMI-1, the specific inhibitor of PRMT1, significantly reduced the cell proliferation of ovarian cancer and abolished the BRD4-ADMA modification in ovarian cancer." (PMID 37737256, 2023). "Our results indicate that arginine methylation of BRD4 by PRMT1 is involved in ovarian cancer tumorigenesis." (PMID 37737256, 2023). "In summary, we demonstrated that PRMT1-mediated asymmetric methylation of BRD4 methylation at R179/181/183 promotes BRD4 phosphorylation and induces ovarian cancer migration and invasion." (PMID 37737256, 2023). "Next, we investigated the response of Ovcar4 tumor models overexpressing BRD4 isoforms in vivo to a combination therapy of cisplatin and paclitaxel (first-line treatment for ovarian carcinoma patients)." (PMID 37705995, 2023). "The ubiquitin-regulated degradation of BRD4 would be a particularly interesting subject of study in ovarian carcinoma." (PMID 37705995, 2023). "Compared to BRD4 wild-type (WT) cells, BRD4 R179/181/183K mutant-expressing cells showed reduced ovarian cancer metastasis." (PMID 37737256, 2023). "We investigated the effects of overexpression or knockdown of individual BRD4 isoforms on ovarian cancer cell proliferation in vitro." (PMID 37705995, 2023). "In ovarian cancer patients, amplification of BRD4 correlates with the overexpression of BRD4-L and BRD4-S mRNAs, as well as the overexpression of BRD4 proteins." (PMID 37705995, 2023). "Noticeably, ovarian cancer cells with forced BRD4-WT expression showed significantly increased cell migration and Transwell invasion compared with vector cells and BRD4-mutant cells." (PMID 37737256, 2023). "To improve clinical relevance of our studies investigating an impact of BRD4 isoforms abundance on ovarian cancer pathogenesis, we used PDX models derived from patients diagnosed with a high-grade serous ovarian carcinoma (HGSOC)." (PMID 37705995, 2023). "Emerging evidence has illustrated that BRD4 is involved in the development of many cancer types, such as pancreatic cancer, colorectal cancer, glioblastoma, and ovarian cancer." (PMID 37737256, 2023). "The response to platinum-taxane chemotherapy in the context of aberrantly activated BRD4 isoform(s) is a highly relevant area of research considering the poor prognosis of ovarian carcinoma patients harboring BRD4 amplification." (PMID 37705995, 2023). "Combined inhibition of BRD4 with ATR/WEE1 is synergistic in ARID1A mutant clear cell ovarian cancer cells." (PMID 37841875, 2023). "BRD4 enrichment was considered a critical component for the detection of potentially oncogenic enhancers due to key observations previously shown in ovarian cancer patients." (PMID 35869079, 2022). "We observed that high levels of BRD2, BRD3, and BRDT indicated a better prognosis, whereas BRD4 predicted poor clinical outcomes in patients with ovarian carcinoma." (PMID 35371325, 2022). "High BRD4 mRNA expression had worse OS for all ovarian cancer patients, HR =1.32 (1.06 - 1.65), P=0.012." (PMID 35371325, 2022). "Our results showed that the protein level of BRD2, BRD3, BRD4, and BRDT in ovarian cancer cell lines was all subsided associated to the normal breast cell (P < 0.05)." (PMID 35371325, 2022). "Nonetheless, investigating enhancers with high BRD4 enrichment can lead to the identification of biomarkers, druggable targets, and an improved understanding of ovarian cancer." (PMID 35869079, 2022). "Namely, across the entirety of the TCGA Pan-Cancer dataset, ovarian cancer patients have the highest rate of genetic amplifications at the BRD4 locus, with ~11% of patients having an amplification of this region 5–7,31." (PMID 35869079, 2022).
ovarian carcinoma (continued). "The downregulation of BRD4 activity markedly reduced the invasive properties of ovarian cancer cell lines, while BRD4 upregulation augmented cell migration and invasion." (PMID 34758842, 2021). "Significantly, miR-765 overexpression-induced anti-ovarian cancer cell activity was largely attenuated by restoring BRD4 expression through an UTR-null BRD4 construct." (PMID 33686960, 2021). "In contrast, miR-765 inhibition by its anti-sense induced BRD4 upregulation to promote ovarian cancer cell proliferation, migration and invasion." (PMID 33686960, 2021). "HGSOC patients harboring focal amplification of the chromosome 19, in regions that encompass BRD4 (19p13.2), tended to show advanced-stage ovarian cancer (97% of the patients were diagnosed with stage III or IV tumors)." (PMID 34758842, 2021). "Perhaps, better understanding of the effects of BRD4 amplification on the initiation and progression of ovarian carcinoma relies on exploring the independent functions of BRD4 isoforms." (PMID 34758842, 2021). "BRD4 directly binds to two independent NRG1 promoter and enhancer sites, and NRG1 has been identified as a direct effector of BRD4 in ovarian carcinoma." (PMID 34758842, 2021). "Collectively, miR-765 inhibition upregulated BRD4 and promoted ovarian cancer cell proliferation and migration." (PMID 33686960, 2021). "In our study, we found that the transcription factor BRD4 positively regulated the transcription of Notch3 and verified this result in a study of ovarian cancer." (PMID 34834420, 2021). "In melanoma, glioma, ovarian cancer, and some other cancers, the overexpression of BRD2 and BRD4 is associated with poor prognosis, and their presence affects the pathways of nuclear factor-κB (NF-κB), Notch, and Hedgehog (Hh) signaling." (PMID 34540687, 2021). "Ovarian cancer cells treated with BETi show a time-dependent reduction in the levels of pCHK1, suggesting that BRD4 can regulate CHK1 signaling in response to DNA replication stress." (PMID 34758842, 2021). "NOTCH3 is another oncogene of high relevance in ovarian carcinoma, which has been recently identified as being directly regulated by BRD4 in HGSOC." (PMID 34758842, 2021). "Significantly, miR-765 overexpression-induced anti-ovarian cancer cell activity was largely inhibited by restoring BRD4 expression using the UTR-null BRD4." (PMID 33686960, 2021). "Despite the evidence that BRD4 amplification in ovarian cancer contributes to poor patient prognosis, little is known about the specific mechanisms by which BRD4 drives tumor progression." (PMID 34758842, 2021). "miR-765 expression levels were downregulated in human ovarian cancer tissues and cells, correlating with the upregulation of BRD4 mRNA." (PMID 33686960, 2021). "PROTACS, such as dBET1 and dBET6, selectively and substoichiometrically degraded BRD4 and demonstrated to be more potent antitumor activity in ovarian carcinoma than the small molecule inhibitors." (PMID 34758842, 2021). "In order to confirm that BRD4 silencing caused miR-765-induced anti-ovarian cancer cell activity, an UTR-null BRD4 construct was transfected to lv-pre-miR-765-Stb-L1 pOC-1 cells." (PMID 33686960, 2021). "Conversely, lv-antagomiR-765-induced miR-765 silencing had opposite effects and it upregulated BRD4 expression in ovarian cancer cells." (PMID 33686960, 2021). "BRD4 is overexpressed in ovarian cancer, required for proliferation and survival of established ovarian cancer cell lines and primary cancer cells." (PMID 33686960, 2021). "Bromodomain-containing protein 4 (BRD4) overexpression promotes ovarian cancer progression, and represents an important therapeutic oncotarget." (PMID 33686960, 2021). "BRD4 regulates PD-L1 transcription in ovarian cancer cells, leading to a decrease in the expression of PD-L1." (PMID 33396954, 2020).
ovarian carcinoma (continued). "This study demonstrated that inhibition of BRD4 via siRNA or the BETi JQ1 increased heterochromatin protein 1 (HP1) in ovarian cancer cells which limited the DDR and increased sensitivity to CHK1i." (PMID 32859084, 2020). "BRD4 plays an important role in the progression and prognosis of various tumors, such as oral squamous cell carcinoma, ovarian cancer, and lymphoma." (PMID 33658927, 2020). "Silencing of BRD4 with shRNA or JQ1 in primary ovarian cancer cells led to reduced proliferation, colony formation cell cycle arrest at G0/G1, and suppressed tumor growth invivo." (PMID 33488950, 2020). "Collectively, these results demonstrated that overexpression of BRD4 reverses shcircSELSR1 mediatied suppression of tumorigenic activity of ovarian cancer cell line SKOV3 and A2780." (PMID 32640974, 2020). "Taken together, our results from the abdominal cavity metastasis model demonstrated that circCELSR1 promotes ovarian cancer progression by stimulating BRD4 expression." (PMID 32640974, 2020). "Taken together, the expression of circCELSR1 and BRD4 were promoted, however, miR-598 expression was suppressed in ovarian cancer cells." (PMID 32640974, 2020). "To investigate the function of circCELSR1 and the putative relative genes miR-598 and BRD4 in regulating ovarian cancer, first we examined the expression of these genes in ovarian cancer cells." (PMID 32640974, 2020). "Collectively, we identified that circCELSR1/miR-598/BRD4 pathway is a new regulatory mechanism in ovarian cancer progression." (PMID 32640974, 2020). "As reported, the protein BRD4 was proven to be necessary for proliferation and survival of two ovarian cell line, and the results of BRD4 inhibition in vitro or in vivo suggested that BRD4 was a potential therapeutic target for ovarian cancer." (PMID 32640974, 2020). "Knockdown of circCELSR1 suppressed proliferation, migration, invasion and epithelial-mesenchymal transition (EMT), but promoted apoptosis in ovarian cancer cells, and these effects were reversed by miR-598 inhibition or BRD4 overexpression." (PMID 32640974, 2020). "Knockdown of circCELSR1 inhibited BRD4-mediated proliferation/migration related signaling via sponging miR-598, thereby repressing ovarian cancer progression." (PMID 32640974, 2020). "Taken together, these studies suggest that aberrant expression of BRD4 promotes ovarian cancer progression and also immune evasion through increased PD-L1 expression." (PMID 33488950, 2020). "In the present study, we identified that circCELSR1 promotes BRD4 expression and ovarian cancer progression via sponging miR-598." (PMID 32640974, 2020). "circCELSR1 knockdown in this two ovarian cancer cell lines resulted in suppression of cell migration, and BRD4 overexpression reversed this effect." (PMID 32640974, 2020). "Taken together, circCELSR1 sponges miR-598 to promote gene expression of BRD4 and facilitates ovarian cancer progression." (PMID 32640974, 2020). "Accordingly, to evaluate the global effect of AZD5153, a novel, potent, and specific BRD4 inhibitor in the TME of ovarian cancer, we profiled BET inhibitory effects on TAMs in vitro and in vivo." (PMID 32184777, 2020). "In this study, we found that the expression of BRD4 was promoted in ovarian cancer cells, which was consistent with previous reports." (PMID 32640974, 2020). "Inhibition of BRD4 by BET inhibitors suppresses ALDH1 activity by targeting ALDH1A1 superenhancer in ovarian cancer." (PMID 32175692, 2020). "We identified two upstream regulators of the DEGs, mir-33 and Brd4, and a pathway analysis identified downstream enrichment of the colorectal cancer metastasis and ovarian cancer metastasis pathways." (PMID 32927694, 2020). "In order to define critical effectors in BRD4-amplified ovarian cancer, we deployed RNA-sequencing to identify genes upregulated in BRD4 long and short-isoform expressing IOSE." (PMID 30036377, 2018).
ovarian carcinoma (continued). "In ovarian cancer, expression of HP1α was repressed by Bromodomain-containing protein 4 (BRD4), which defects DNA damage response to facilitate tumorigenesis." (PMID 29903985, 2018). "Further, of all cancer types tested for BRD4 protein expression by RPPA in cBioPortal, ovarian cancer exhibits the highest level of BRD4 protein expression." (PMID 30036377, 2018). "To study the functional consequences of BRD4 amplification in ovarian cancer, we surveyed BRD4 copy-number across the Cancer Cell Line Encyclopedia (CCLE)." (PMID 30036377, 2018). "In the 12 ovarian cancer cell lines tested, the level of BRD4 mRNA positively correlated with JQ1 IC50 (R2 = 0.49)." (PMID 30036377, 2018). "In order to assess the oncogenic potential of BRD4 in ovarian cancer, we examined the anchorage-independent growth potential of BRD4 long and short-isoform expressing IOSE cells." (PMID 30036377, 2018). "BRD4 is of interest as a therapeutic target in hematological and solid tumors including ovarian cancer." (PMID 28881656, 2017). "Among 72 and 10 such genes identified in colorectal and ovarian tumors, respectively, the most frequently mutated genes BRD4 and MLL2 (62 % of colorectal tumors) and ARID1A (50 % of ovarian carcinomas) are involved in epigenetic regulation." (PMID 29296220, 2017). "Another in vivo shRNA screen identified BRD4 as a therapeutic target, demonstrating that BRD4 inhibitor (JQ1) decreased survival of high MYC-expressing ovarian cancer cells." (PMID 27558154, 2016). "Recently, bromodomain and extraterminal (BET) domain protein BRD4 has been identified as a potential therapeutic target in ovarian cancer." (PMID 26575423, 2016). "Furthermore, BRD4, an acetylation reader protein, regulates gene expression in ovarian cancer by recognizing acetylated histones." (PMID 40003691, 2025). "Ovarian cancer patients have the highest overall expression of BRD4 and the highest rate of genetic amplifications at the BRD4 locus across the entirety of the TCGA Pan-Cancer dataset; ~11% of patients with ovarian cancer have an amplification of the region containing the BRD4 gene." (PMID 38542080, 2024). "Large studies are required to further assess the prognostic role of BRD4 in ovarian cancer." (PMID 38893083, 2024). "Treatment with OPT-0139 decreased BRD4 expression in the ovarian cancer cell lines." (PMID 38473320, 2024). "Silencing of BRD4 by hsa-miR-765 resulted in substantial anti-ovarian cancer activity." (PMID 39003404, 2024). "We hypothesized that a BRD4 inhibitor may have an anticancer effect either alone or in combination with cisplatin in preclinical settings with ovarian cancer." (PMID 38473320, 2024). "In addition, HDAC inhibitors increased ALDH1A1 expression through the transcription factor BRD4 in ovarian cancer cells." (PMID 37954205, 2023). "Here, we described the crucial role of BRD4 arginine methylation in ovarian cancer metastasis." (PMID 37737256, 2023). "Considering the emerging view of BRD4 as a general regulator of transcriptional regulation and its prominent role in cancer development, we focused on subsequent investigations on the molecular role of BRD4 in ovarian cancer cells." (PMID 38201534, 2023). "Overall, our work revealed a strong positive correlation between BRD4 overexpression status and chemoresistance in ovarian cancer, which could be explored to develop a prognostic strategy to predict a patient response to platinum/taxane-based chemotherapy." (PMID 37705995, 2023). "Our data also revealed a strong positive correlation between BRD4 overexpression status and chemoresistance in ovarian cancer, which could serve as a prognostic tool to predict chemotherapy treatment outcomes in ovarian cancer patients." (PMID 37705995, 2023). "Collectively, we propose that one of the mechanisms driving chemoresistance in ovarian carcinoma with amplified BRD4 could be an increased DNA damage and generation of polyploid giant cells that arise as a result of BRD4-S overexpression." (PMID 37705995, 2023).